RABGEF1 (RAB guanine nucleotide exchange factor 1)
Description:
Acts as a guanine-nucleotide releasing factor (GEF) for RAB5A by promoting the conversion of inactive RAB-GDP to the active form RAB-GTP. Forms a complex with RABEP1 that acts as Rab4/Rab5 effector regulating endosome fusion. Involved in endocytic membrane fusion and membrane trafficking of recycling endosomes. Also functions as a ubiquitin ligase (By similarity).
Synonyms: RABEX5; rabex-5; RAP1
Tractability: PROTAC: UniProt records ubiquitination sites on it; ubiquitination databases record sites on it; its protein half-life has been measured.
Gene: Protein-coding gene on chromosome 7 (66,682,105 to 66,811,464, forward strand). Ensembl gene ENSG00000154710.
Subcellular location: Cytoplasm; Early endosome; Recycling endosome
Subcellular location (Human Protein Atlas): Cytosol; Nucleoli
Pathways (Reactome):
Vesicle-mediated transport: RAB GEFs exchange GTP for GDP on RABs; TBC/RABGAPs
Gene Ontology:
Molecular function: guanyl-nucleotide exchange factor activity; protein binding; small GTPase binding; DNA binding; ubiquitin protein ligase activity; zinc ion binding
Biological process: endosomal transport; protein targeting to membrane; dendritic transport; vesicle-mediated transport
Cellular component: cytosol; early endosome; early endosome membrane; endocytic vesicle; cytoplasm; dendrite; presynaptic endosome; recycling endosome; vesicle
Genetic constraint (gnomAD): Loss-of-function variants: 26 observed, 52.17 expected, observed/expected ratio (o/e) 0.5, 90% interval 0.36 to 0.69. The upper end of that interval is the gene's LOEUF score, 0.69, which puts it in group 2 of 6, group 1 being the genes least tolerant of losing a copy. Missense variants: 459 observed, 608.65 expected, observed/expected ratio (o/e) 0.75, 90% interval 0.7 to 0.81. Synonymous variants: 183 observed, 212.67 expected, observed/expected ratio (o/e) 0.86, 90% interval 0.76 to 0.97.
Homologues: Orthologues: chimpanzee RABGEF1 (100% identical), macaque RABGEF1 (99% identical), rabbit RABGEF1 (98% identical), pig RABGEF1 (97% identical), dog RABGEF1 (97% identical), guinea pig RABGEF1 (96% identical), mouse Rabgef1 (96% identical), rat Rabgef1 (95% identical), tropical clawed frog rabgef1 (80% identical), zebrafish rabgef1 (72% identical), Drosophila melanogaster Rabex-5 (35% identical), Caenorhabditis elegans rabx-5 (31% identical). Paralogues in human: RIN2 (20% identical), RIN3 (19% identical), RIN1 (17% identical), GAPVD1 (15% identical), RINL (14% identical), VPS9D1 (12% identical).
Diseases named in the same sentence as RABGEF1 in open-access papers:
RABGEF1 is named in the same sentence as 18 diseases in open-access papers, as found by Europe PMC text mining. Sharing a sentence is not in itself a finding about the gene and the disease. The quoted sentences say what the papers report.
leukaemias (2 papers, 2010 to 2015). "Even though Rabgef1 expression pattern is more erythroid, it was amplified in all other Graffi-induced leukaemias and in all the tested human cell lines, indicating its ubiquitous expression in haematopoietic cells." (PMID 20102610, 2010). "Rabgef1 has never been reported in relation to erythroid lineage or leukaemia and the encoded protein is known to interact with Rab5, Rab21 or Rab22." (PMID 20102610, 2010). "Moreover, numerous genes are being reported for the first time and some of these genes are candidate oncogenes: Fgf3, Nmyc, Fap, Myct1, Gucy1a3, Gulp1 and Fkbp9 specific to megakaryoblastic leukaemias and Ssx2ip, Rab11a, Ncoa3, Snca, Ltbp2, Rabgef1 and Btbd14a specific to erythroleukaemias." (PMID 20102610, 2010).
retinal degeneration (2 papers, 2020 to 2025). Degeneration of the retina. "We demonstrate that loss of RabGEF1 in mice causes specific developmental defects during photoreceptor outer segment formation, leading to visual dysfunction as early as eye opening followed by retinal degeneration." (PMID 33362196, 2020).
gliosarcoma (1 paper, 2019). A rare histological variant of glioblastoma (WHO grade IV) characterized by a biphasic tissue pattern with alternating areas displaying glial and mesenchymal differentiation (WHO). "As RABGEF1 was linked to the development of some cancers this alteration may have importance in gliosarcoma development." (PMID 30818875, 2019). "An interesting translocation between RABGEF1 and GTF2IRD1P1 genes was discovered in three gliosarcoma samples." (PMID 30818875, 2019).
retinal disease (1 paper, 2020). "Dark rearing that slows photoreceptor degeneration in several retinal disease models (e.g., those with dominant rhodopsin mutations or with loss of the visual arrestin) did not have any impact on visual responses of Rabgef1-/- mice." (PMID 33362196, 2020).
tumor (11 papers, 2013 to 2024). "Here, the authors show that tumor cell-intrinsic ATP6V0A1 drives RABGEF1-dependent cholesterol absorption and thus triggers paracrine TGF-β1/SMAD3 signaling to inactive memory CD8+ T cells in CRC." (PMID 38971819, 2024). "Moreover, significant colocalization of ATP6V0A1 and RABGEF1 or TGF-β1 was observed in the tumor tissues with high ATP6V0A1." (PMID 38971819, 2024). "Importantly, we revealed tumor cell-intrinsic ATP6V0A1 as a novel immunosuppressive factor that promotes RABGEF1-dependent cholesterol absorption in CRC cells, consequently initiating paracrine TGF-β1/SMAD3 signaling to deactivate memory CD8+ T cells." (PMID 38971819, 2024). "Within the tumor tissues with ATP6V0A1 expression, both expression of RABGEF1 and TGF-β1 were relatively higher in the areas with high ATP6V0A1 rather than those with low ATP6V0A1 (upper)." (PMID 38971819, 2024). "On the other hand, both RABGEF1 and TGF-β1 were rarely detected in the tumor tissues with minimal detection of ATP6V0A1 (lower)." (PMID 38971819, 2024). "The downregulated expression of IL-1, CTSW, NR1H3 and CCR8 (with HR < 1) indicated these molecules as tumor suppressors, whereas the upregulated expression levels of LY86, RABGEF1, CYFIP2 and SERINC3 (with HR > 1) indicated these molecules as oncogenes." (PMID 33816214, 2020).
cancer (6 papers, 2013 to 2024). A tumor composed of atypical neoplastic, often pleomorphic cells that invade other tissues. "RAB guanine nucleotide exchange factor 1 (RABGEF1) is implicated in the development of certain human cancers." (PMID 30818875, 2019).
retinopathies (1 paper, 2020). "We propose that RabGEF1 and associated components are potential candidates for syndromic traits that include a retinopathy phenotype." (PMID 33362196, 2020). "We suggest that RabGEF1 and related components should be considered as candidates for human retinopathies and/or syndromes that include a photoreceptor degeneration phenotype." (PMID 33362196, 2020).
RABGEF1 also shares sentences with these, for which no sentence is quoted: breast carcinoma (2 papers); gastric cancer (2); lymph node metastasis (2); acute myeloid leukemia (1); Alzheimer’s dementia (1); benign breast tumor (1); benign tumor (1); colorectal cancer (1); metastasis (1); neurodevelopmental disorder (1); prostate carcinoma (1).